MMP9 (matrix metallopeptidase 9)
Diseases named in the same sentence as MMP9 in open-access papers (continued):
Sharing a sentence is not in itself a finding about the gene and the disease.
female genital prolapse (2 papers, 2019 to 2022). "Changes in the genes that encode MMP9 could interfere with the genesis of POP; thus, the objective of the present study was to evaluate polymorphisms of the C-1562T MMP9 gene as a risk factor related to the occurrence of female genital prolapse." (PMID 30939607, 2019). "The results indicated that the occurrence of uterine prolapse was positively correlated with age, postmenopausal age, and MMP-2 and MMP-9 expression (p < 0.01), and negatively correlated with CD44 expression (p < 0.05)." (PMID 35910471, 2022). "The occurrence of uterine prolapse was positively correlated with age, postmenopausal age, and MMP-2 and MMP-9 expression (p < 0.01) and negatively correlated with CD44 expression (p < 0.05)." (PMID 35910471, 2022).
fungal keratitis (2 papers, 2009 to 2023). "MMP-9 increases during fungal keratitis and is capable of promoting angiogenesis during stromal degradation." (PMID 19816603, 2009).
generalized tonic-clonic seizures (2 papers, 2013 to 2022). "Serum level of MMP-9 is increased after tonic-clonic seizures (TCS) at 30 min, 2, 6, and 24 h and returns to normal at 72 h." (PMID 36499038, 2022).
geographic atrophy (2 papers, 2021 to 2022). "Recent studies demonstrate significant differences in plasma concentrations of MMP-9, TIMP-1, and TIMP-3 proteins in patients with AMD: higher levels of TIMP-1 and MMP-9 in patients with geographic atrophy (GA) and lower levels of TIMP-3 and lower TIMP-3/MMP-2 ratios in patients with CNV." (PMID 35155457, 2021).
gingival overgrowth (2 papers, 2020 to 2024). Excessive growth of the gingiva either by an increase in the size of the constituent cells (gingival hypertrophy) or by an increase in their number (gingival hyperplasia). "The study investigated the expression of HIF-1, Gla-3 and MMP-9 in tissue samples of OLP compared to control subjects of un-inflamed gingival overgrowth." (PMID 38951854, 2024). "Our findings suggest a novel mechanism triggered by SPOCK1 interactions with TGF-β1 and MMP-9 that induces several signaling pathways in drug-induced gingival overgrowth." (PMID 32555336, 2020). "We demonstrated that the expression of SPOCK1, TGF-β1, and MMP-9 in calcium channel blocker-induced gingival overgrowth is higher than that in non-overgrowth tissues." (PMID 32555336, 2020). "We found that SPOCK1, TGF-β1, and MMP-9 mRNA and their protein products were significantly higher in gingival overgrowth (GO) samples compared to non-overgrowth controls." (PMID 32555336, 2020). "The results revealed a significant increase in immune expression of MMP-9 by epithelial cells mainly basal layer and the sub-epithelial infiltrate of lymphocytes in A-ELP compared to non-inflamed gingival overgrowth." (PMID 38951854, 2024).
granulomatosis with polyangiitis (2 papers, 2022 to 2024). A small-vessel necrotizing vasculitis characterized by the association of inflammation of the vessel wall and peri- and extravascular granulomatosis. "Finally, a fascinating relationship has been described between neutrophils forming extracellular traps (NETs) and MMP-9 induction in granulomatosis with polyangiitis (GPA)." (PMID 39086970, 2022).
hay fever (2 papers, 2024 to 2025). "As OA is also an inflammatory condition, we explored the potential of MMP-9 in predicting OA among hay fever sufferers." (PMID 41009673, 2025). "This study examined two tear biomarkers of inflammation: tear IgE and MMP-9, generating novel and confirmatory findings that contribute meaningfully to the evolving understanding of tear biomarkers in OA among hay fever sufferers." (PMID 41009673, 2025). "However, we found an increase in the levels of MMP-9 among the hay fever group, when compared to HCs, a possible indicator of disrupted barrier function on the corneal epithelium due to friction." (PMID 41009673, 2025). "Hence, this study could not address the usefulness of MMP-9 as a tear biomarker in OA among hay fever sufferers." (PMID 41009673, 2025).
HELLP syndrome (2 papers, 2017 to 2023). A life-threatening condition that can potentially complicate pregnancy. "Similar to our present study, plasma level of MMP-9 was found to be down-regulated in pregnancies that later developed HELLP syndrome." (PMID 28143958, 2017).
hemophilia (2 papers, 2020 to 2024). Hemophilia is a genetic disorder characterized by spontaneous hemorrhage or prolonged bleeding due to factor VIII or IX deficiency. "Other studies reported elevated levels of plasma MMP-9, SDF-1α, soluble VCAM-1, and several other markers in patients with hemophilia, though results for some markers were inconsistent." (PMID 39337384, 2024).
hepatitis B (2 papers, 2022 to 2023). "Its mechanisms could be related to reducing the expression of MMP9, and pathways such as pathways in cancer, hepatitis B, TNF signaling pathway, and MAPK signaling pathway." (PMID 35330838, 2022). "Moreover, Hepatitis B virus infection induces MMP-9 expression in immune cells, thereby evading host immunity by binding MMP-9 to IFN receptor I and blocking IFN signaling." (PMID 37447286, 2023).
hepatoblastoma (2 papers, 2022 to 2023). Hepatoblastoma (HB) is a malignant hepatic tumor and is the most common pediatric liver cancer. "In the study of Zhang and colleagues, low dosages of ATO decreased the formation of vasculogenic mimicry (VM) in hepatoblastoma cells in vitro and in vivo via reducing the expression levels of VM-associated proteins such as VE-cadherin and MMP-9." (PMID 38275666, 2023).
herpes simplex (2 papers, 2021 to 2022). "Neutrophils can stimulate angiogenesis via matrix metalloproteinase-9 (MMP-9) due to herpes simplex infection." (PMID 34603282, 2021).
hilar cholangiocarcinoma (2 papers, 2013 to 2019). A cholangiocarcinoma that arises from the junction, or adjacent to the junction, of the right and left hepatic ducts. "Preoperative serum MMP-9 has high predictive value for prognosis and is an independent influencing factor for the prognosis of patients with hilar cholangiocarcinoma." (PMID 31038586, 2019). "OD analysis of VEGFR-2, Gab1 and MMP-9 expression in hilar cholangiocarcinoma tissues and biliary duct tissues with chronic inflammation." (PMID 24312291, 2013). "In this study, immunohistochemistry was first used to detect and analyze the expression of Gab1, VEGFR-2, and MMP-9 in hilar cholangiocarcinoma solid tumors and the relationships to the clinical pathological features." (PMID 24312291, 2013). "Gab1 regulates growth, apoptosis and invasion through the VEGFR-2/Gab1/PI3K/Akt signaling pathway in hilar cholangiocarcinoma cells and influences the invasion of tumor cells via MMP-9." (PMID 24312291, 2013). "Correlation between Gab1 and VEGFR-2, Gab1 and MMP-9, and VEGFR-2 and MMP-9 expression in hilar cholangiocarcinoma tissues." (PMID 24312291, 2013). "In summary, experimental results demonstrate that VEGFR-2, Gab1 and MMP-9 are closely correlated with hilar cholangiocarcinoma and that Gab1 or VEGFR-2 up-regulates growth and invasion and down-regulates apoptosis in ICBD-1 cells via the PI3K/Akt pathway." (PMID 24312291, 2013). "In this study, we detected VEGFR-2, Gab1 and MMP-9 expression in solid tumor hilar cholangiocarcinoma tissues to study their interactions and relationships with the clinical and pathological characteristics of hilar cholangiocarcinoma." (PMID 24312291, 2013). "Relationship between VEGFR-2, Gab1 and MMP-9 expression in hilar cholangiocarcinoma tissues and patient clinical and pathological parameters." (PMID 24312291, 2013). "Gab1, VEGFR-2, and MMP-9 were highly expressed and positively correlated with each other in hilar cholangiocarcinoma tissues, which were related to lymph node metastasis and differentiation." (PMID 24312291, 2013). "Finally, we detected MMP-9 levels in hilar cholangiocarcinoma tumor cells after down-regulation of Gab1 and VEGFR-2." (PMID 24312291, 2013). "We presumed that VEGFR-2, Gab1 and MMP-9 likely play roles in hilar cholangiocarcinoma." (PMID 24312291, 2013). "Because our results showed a positive relationship among VEGFR-2, Gab1 and MMP-9 in hilar cholangiocarcinoma, we proposed that the VEGFR-2/Gab1/PI3K/Akt signaling pathway was likely present in hilar cholangiocarcinoma and could influence MMP-9 expression." (PMID 24312291, 2013). "Evaluation of hilar cholangiocarcinoma specimens showed that VEGFR-2, Gab1 and MMP-9 were all closely correlated with hilar cholangiocarcinoma and its malignant biological behaviors and were related to each other." (PMID 24312291, 2013). "Because the VEGFR-2/Gab1/PI3K/Akt signaling pathway promotes cell growth and invasion and MMP-9 is one important downstream target protein of PI3K/Akt, we presumed that they may play roles in hilar cholangiocarcinoma." (PMID 24312291, 2013). "Furthermore, Gab1 and VEGFR-2 siRNA were used to interfere the hilar cholangiocarcinoma cell line ICBD-1 and then detect the PI3K/Akt signaling pathway, MMP-9 levels and malignant biological behaviors of tumor cells." (PMID 24312291, 2013).
Hip dysplasia (2 papers, 2020 to 2024). The presence of developmental dysplasia of the hip. "It has been found that the CpG site located near the transcriptional initiation point of MMP-9 promoter in hip dysplasia (DDH) is severely demethylated compared with the control group." (PMID 32695308, 2020). "A panel consisting of four biomarkers (urinary C-telopeptide fragments of type I collagen CTX-I and type II collagen, serum MMP-9 and Procollagen II C-Terminal Propeptide PIICP) was determined to be highly discriminatory in detecting the presence or absence of hip dysplasia in adult dogs." (PMID 39582715, 2024).
hip fracture (2 papers, 2013 to 2016). Traumatic or pathological injury to the hip in which the continuity of either the femoral head, femoral neck, intertrochanteric or subtrochanteric regions is broken. "On the other hand, the pro-MMP-9 complexed with neutrophil gelatinase-associated lipocalin form (130 kDa) was a predictor of gait status recovery 6 months after hip fracture." (PMID 23437384, 2013). "Our data showed that the pro-MMP-9 was associated with gait status recovery 6 months after hip fracture." (PMID 23437384, 2013). "In conclusion, our data suggested that serum pro-MMP-9 is a predictor of gait status recovery 6 months after hip fracture." (PMID 23437384, 2013). "In conclusion, serum pro-MMP-9 is a predictor of gait status recovery 6 months after hip fracture." (PMID 23437384, 2013).
Huntington disease (2 papers, 2013 to 2025). Huntington disease (HD) is a rare neurodegenerative disorder of the central nervous system characterized by unwanted choreatic movements, behavioral and psychiatric disturbances and dementia. "Previous multi-cohort meta-analyses and experimental studies confirmed that MMP9 and S100A8/A9 contribute to microglial activation and neuronal injury, while CCL2 signaling has been linked to neurodegeneration and immune cell recruitment in Huntington’s disease." (PMID 41614741, 2025).
hyperandrogenism (2 papers, 2022 to 2023). Excessive secretion of androgens from the adrenal glands or gonads. "Upregulation of MMP9 could contribute to excess abdominal adiposity and hyperandrogenism, which might be related to increased cardiovascular risk in PCOS." (PMID 37537636, 2023).
Hypercalciuria (2 papers, 2020 to 2021). "In addition, apoptosis and calcium crystal deposition were significantly reduced in Sprague–Dawley rats with 1,25(OH)2D3-induced hypercalciuria following MMP-9 inhibitor I treatment." (PMID 34211634, 2021).
Hypothermia (2 papers, 2021 to 2023). Reduced body temperature due to failed thermoregulation. "Hypothermia is associated with reduced levels of MMP9 as compared with non-hypothermia after CA, whereas serum MMP9 level in the CA patients was increased compared with healthy human controls." (PMID 34261545, 2021).
inflammatory skin disease (2 papers, 2024 to 2025). Inflammatory skin disorders covers a broad category that includes many conditions ranging in severity, from mild itching to grave medical health complications These disorders are common in people of all ages and races. "TNF-α plays a central role in the pathogenesis of inflammatory skin disorders by activating endothelial and dermal cells, thereby upregulating downstream mediators such as IL-6 and MMP-9." (PMID 41404493, 2025). "TNF-α stimulation led to a significant upregulation of MMP-9 secretion, which was markedly reduced following treatment with Withaferin A-loaded liposomal gel, further emphasising the potential of Withaferin A formulations to modulate tissue remodelling in inflammatory skin disorders." (PMID 41404493, 2025). "Thus, MMP-2 and MMP-9 play important roles in inflammatory skin diseases." (PMID 39062816, 2024).
insomnia (2 papers, 2016 to 2022). A sleep disorder characterized by difficulty in falling asleep and/or remaining asleep. "MMP9 is an inflammatory protein that proved to be a potential target of action in the treatment of insomnia." (PMID 35958162, 2022). "In the results, HP, FGA, FGG, FGB, and MMP9 were upregulated in patients with insomnia, and FN1, APP, EGF, AHSG, and IGF1 were downregulated compared with controls." (PMID 35958162, 2022). "Among them, HP, MMP9, FGA, FGB, and FGG were validated as upregulated, and APP, AHSG, and IGF1 were downregulated in patients with insomnia." (PMID 35958162, 2022).
iron deficiency (2 papers, 2021 to 2024). "Iron deficiency enhances atheroma inflammation through the p38 MAPK-NF-κB-EMMPRIN/MMP-9 pathway." (PMID 38509409, 2024). "By using a p38 inhibitor and an NF-κB inhibitor, it was established that iron deficiency-induced induction of EMMPRIN and MMP-9 requires consecutive upstream activation of p38 MAPK and NF-κB." (PMID 38509409, 2024). "Iron deficiency enhances EMMPRIN expression, MMP-9 production, and MMP-9 enzymatic activity in THP-1-derived macrophages and foam cells." (PMID 38509409, 2024). "A retinal X receptor agonist suppresses the effects of iron deficiency on EMMPRIN, MMP-9, and NF-κB but not on MAPK activation." (PMID 38509409, 2024).
Japanese encephalitis (2 papers, 2016 to 2022). A disease due to a virus transmitted by an arthropod). "In the case of ZO-1, Japanese encephalitis viral infected astrocytes induce the expression of VEGF, IL-6, and MMP2/MMP-9 that upregulate the expression of the E3-Ub-ligase component n-recognin-1 that triggers ZO-1 ubiquitination and degradation." (PMID 36291162, 2022).
kidney injury (2 papers, 2022). Trauma to the kidney. "Additionally, several studies have shown that inhibition of MMP-2 and MMP-9 protects against AKI, as they are increased in the acute phase of kidney injury and modulate tubular/microvascular damage." (PMID 35629096, 2022).
lactic acidosis (2 papers, 2016 to 2021). Metabolic acidosis characterized by the accumulation of lactate in the body. "Lactic acidosis results in overexpression of matrix metalloproteinase-9 (MMP-9), VEGF-A, transforming growth factor-β2 (TGF-β2) and IL-8 in various cancer cells, rendering the TME even more complicated." (PMID 28077918, 2016).
Large vessel vasculitis (2 papers, 2022 to 2026). A type of vasculitis (inflammation of blood vessel walls) affecting large arteries such as the aorta and branches of the aorta. "MMP-9 also plays a major role in large-vessel vasculitis by controlling the access of monocytes and T cells to the vascular wall since T cells depend on MMP-9 producing monocytes to pass through collagen IV membranes." (PMID 35629030, 2022).
larynx cancer (2 papers, 2019 to 2020). A primary or metastatic malignant neoplasm involving the larynx. "Most studies on the role of MMP-9 and TIMP-1 are related to the evaluation of the expression of these proteins in larynx cancer compared to the controls." (PMID 31143300, 2019).
latent infection (2 papers, 2021 to 2025). "Interestingly, KSHV (though not HPV31) latent infection also upregulated MMP9 protein levels in serum-free keratinocyte basal media, while our previous work showed that KSHV K1 protein induced MMP9 expression in endothelial cells." (PMID 40815147, 2025).
Left ventricular dilatation (2 papers, 2022 to 2023). Enlargement of the chamber of the left heart ventricle. "These authors demonstrated that TNF-α blockade decreased left ventricular dilation, which was associated with a decrease in the production and activity of MMP-9." (PMID 35372112, 2022).
leiomyoma (2 papers, 2021 to 2023). A well-circumscribed benign smooth muscle neoplasm characterized by the presence of spindle cells with cigar-shaped nuclei, interlacing fascicles, and a whorled pattern. "Here, we studied TEM1, MMP-2 and MMP-9 expression in 50 samples of uterine leiomyosarcoma (n = 25) and leiomyoma (n = 25) tissues." (PMID 36639546, 2023). "However, in our study, MMP-9 was 72% negative (21 of 25) or only weakly expressed (median Long-H score of 80) in uterine leiomyosarcoma which was similar to that of leiomyoma tissues (22 of 25 negative)." (PMID 36639546, 2023). "Since leiomyoma progression is related to increases in extracellular matrix (ECM) accumulation and matrix metalloproteinase (MMP), BHT could effectively increase ECM-related protein expression, as well as MMP-2 and MMP-9 protein expression." (PMID 34578952, 2021).
leiomyosarcoma (2 papers, 2013 to 2023). An uncommon, aggressive malignant smooth muscle neoplasm, usually occurring in post-menopausal women. "Uterine leiomyosarcoma showed strong bands corresponding to inactive and active MMP-9 and a faint band corresponding to MMP-9 dimer induced with PMA treatment, but no MMP-2 band." (PMID 23661254, 2013). "Uterine leiomyosarcoma SK-UT-1 demonstrated a positive correlation between u-PA and MMP-9." (PMID 23661254, 2013). "For uterine leiomyosarcoma SK-UT-1 cells, a significant negative correlation (r=−0.956) was found between NM modulation of Matrigel invasion inhibition and MMP-9 secretion." (PMID 23661254, 2013). "As anticipated, a significant positive correlation was found between the secretion of u-PA and MMP-9 and a significant negative correlation was found between MMP-9 and TIMP-2 and between u-PA and TIMP-2 secretion by leiomyosarcoma SK-UT-1 cell line." (PMID 23661254, 2013). "Furthermore, we found that TEM1 and MMP-2 expression was positively correlated with tumor stage, implying that MMP-2, rather than MMP-9, might participate in TEM1-mediated tumorigenesis of uterine leiomyosarcoma." (PMID 36639546, 2023). "MMP-2, but not MMP-9, might work together with TEM1 in uterine leiomyosarcoma progression." (PMID 36639546, 2023).
lichen planus (2 papers, 1998 to 2024). A chronic, recurrent, pruritic inflammatory disorder of unknown etiology that affects the skin and mucus membranes. "In oral lichen planus samples, immunopositivity for MMP-9 was identified by most of the epithelial cells mainly the basal layer cells and the sub-epithelial lymphocytic infiltrate." (PMID 38951854, 2024). "Using zymography, elevated levels of MMP-2 and MMP-9 were observed in carcinoma samples in comparison with lichen planus or normal oral mucosa." (PMID 9649139, 1998).
Lipedema (2 papers, 2020 to 2023). Disorder of adipose tissue characterized by symmetric and bilateral enlargement of the lower extremities due to abnormal deposition of subcutaneous fat often in obese women. "Furthermore, this model will be used to screen potential drugs targeting the angiogenic markers, such as VEGF, ANG2, and MMP9, which will help reduce adipocyte hypertrophy and the formation of dysfunctional microvasculature, thereby providing new treatment opportunities for lipedema." (PMID 37686378, 2023). "The data show a decrease in gene expression of MMP2, MMP9 and MMP11 in lipedema-differentiated spheroids as compared to lipedema-undifferentiated and healthy spheroids." (PMID 33171717, 2020).